Y_RNA (Y RNA )
Gene: Miscellaneous RNA gene on chromosome 15 (45,591,984 to 45,592,085, forward strand). Ensembl gene ENSG00000200419.
Homologues: Orthologues: chimpanzee Y_RNA (99% identical), macaque Y_RNA (98% identical), guinea pig Y_RNA (94% identical). Paralogues in human: Y_RNA (93% identical), RNY3 (92% identical), Y_RNA (92% identical), Y_RNA (91% identical), RNY3P1 (90% identical), Y_RNA (90% identical), Y_RNA (89% identical), RNY3P14 (88% identical), Y_RNA (88% identical), RNY3P16 (87% identical), Y_RNA (87% identical), RNY3P3 (86% identical), and 98 more.